NCOA7 (nuclear receptor coactivator 7)
Description:
Transcriptional coactivator which enhances the transcriptional activities of several nuclear receptors including ESR1, THRB, PPARG and RARA. Inhibits the activity of the vacuolar-type ATPase (V-ATPase) by inducing disassembly of the V-ATPase complex. Protects the Golgi apparatus lumen from excess acidification by inhibiting V-ATPase ATP hydrolytic activity through interaction with V-ATPase catalytic subunit ATP6V1A, maintaining optimal conditions for glycosylation enzymes (By similarity). Required to stabilize V-ATPase V1 subunits ATP6V1B2 and ATP6V1A at membrane sites (By similarity). Involved in protection against oxidative damage. Involved in urine acidification (By similarity). [Isoform 1]: Exhibits oxidation resistance activity. Protects neuronal cells from oxidative stress with weaker neuroprotective activity than isoform 5 (By similarity). [Isoform 5]: Exhibits oxidation resistance activity. Protects neuronal cells from oxidative stress with stronger neuroprotective activity than isoform 1 (By similarity). Inhibits endosome-mediated viral entry by inhibiting fusion of the viral and endosomal membranes and subsequent nuclear translocation of viral ribonucleoproteins. Promotes increased cytoplasmic vesicular acidification, lysosomal protease activity and the degradation of endocytosed material.
Synonyms: ERAP140; ESNA1; Nbla00052; Nbla10993; dJ187J11.3; TLDC4; NCOA7-AS
Tractability: PROTAC: ubiquitination databases record sites on it; its protein half-life has been measured.
Gene: Protein-coding gene on chromosome 6 (125,780,943 to 125,932,034, forward strand). Ensembl gene ENSG00000111912.
Subcellular location: Nucleus; Cytoplasm; Golgi apparatus, cis-Golgi network membrane; Golgi apparatus, trans-Golgi network membrane; Cytoplasm (Isoform 5)
Subcellular location (Human Protein Atlas): Nuclear bodies; Nucleoplasm; Golgi apparatus
Gene Ontology:
Molecular function: nuclear receptor binding; protein binding; transcription coactivator activity
Biological process: positive regulation of transcription by RNA polymerase II; regulation of transcription by RNA polymerase II; response to oxidative stress
Cellular component: nucleus; cytoplasm; Golgi apparatus
Genetic constraint (gnomAD): Loss-of-function variants: 35 observed, 89.17 expected, observed/expected ratio (o/e) 0.39, 90% interval 0.3 to 0.52. The upper end of that interval is the gene's LOEUF score, 0.52, which puts it in group 2 of 6, group 1 being the genes least tolerant of losing a copy. Missense variants: 955 observed, 1,084.6 expected, observed/expected ratio (o/e) 0.88, 90% interval 0.83 to 0.93. Synonymous variants: 371 observed, 398.69 expected, observed/expected ratio (o/e) 0.93, 90% interval 0.85 to 1.01.
Homologues: Orthologues: chimpanzee NCOA7 (99% identical), macaque NCOA7 (98% identical), dog NCOA7 (89% identical), pig NCOA7 (88% identical), rabbit NCOA7 (88% identical), guinea pig NCOA7 (83% identical), mouse Ncoa7 (82% identical), rat Ncoa7 (82% identical), tropical clawed frog ncoa7 (58% identical), zebrafish ncoa7a (15% identical), zebrafish ncoa7b (14% identical). Paralogues in human: OXR1 (37% identical), TLDC2 (10% identical), MEAK7 (9% identical).
Diseases named in the same sentence as NCOA7 in open-access papers:
NCOA7 is named in the same sentence as 35 diseases in open-access papers, as found by Europe PMC text mining. Sharing a sentence is not in itself a finding about the gene and the disease. The quoted sentences say what the papers report.
breast carcinoma (7 papers, 2016 to 2024). "In the present study, it was shown that the nuclear receptor (particularly ER) co-activator NCOA7 was overexpressed in breast tumors and its expression was reversely associated with the overall survival of patients with breast cancer." (PMID 38699661, 2024). "Studies using IHC staining of NCOA7 in breast tumor tissue samples indicated that its expression was associated with tumor size and lymph node metastasis of breast cancer." (PMID 38699661, 2024). "The association between the expression of NCOA7 and the overall survival of patients with breast cancer was determined by K-M analysis." (PMID 38699661, 2024). "By performing these studies, it is expected that the molecular mechanism underlying the promoting effect of NCOA7 on breast cancer progression will be revealed." (PMID 38699661, 2024). "It is shown by genome-wide association studies that several gene polymorphisms of NCOA7 were associated with the development of breast cancer." (PMID 27509054, 2016). "Therefore, it is proposed that NCOA7 is a prognostic biomarker associated with poor survival of patients with breast cancer." (PMID 38699661, 2024). "The results indicated that NCOA7 was overexpressed in breast tumors and that its expression was reversely associated with the survival of patients with breast cancer, suggesting that it may be a biomarker for poor prognosis of breast cancer." (PMID 38699661, 2024). "Genetic variations of the NCOA7 gene are associated with a reduced risk of breast cancer." (PMID 38699661, 2024). "Taken together, these results indicate that the expression of NCOA7 is associated with poor prognosis of breast cancer and suggest that this protein may be a driver for metastasis and a potential therapeutic target for advanced breast cancer." (PMID 38699661, 2024). "Interestingly, NCOA7 (Nuclear Receptor Coactivator 7) has been reported to have gene polymorphisms associated with breast cancer development and it has also been identified as a potential biomarker in oral squamous cell carcinoma." (PMID 36229806, 2022). "Several gene polymorphisms of NCOA7 have been associated with the development of breast cancer." (PMID 31481962, 2019). "In addition, NCOA7 exhibits a genetic polymorphism associated with the development of breast cancer, and genetic variations in its locus may reduce susceptibility to breast cancer." (PMID 37511343, 2023). "The present study aimed to determine the expression levels of NCOA7 in breast tumor samples and confirmed its potential utility as a breast cancer prognostic biomarker." (PMID 38699661, 2024). "The mean survival time of NCOA7-positive patients with breast cancer was 84.738±3.536 months, while that of the NCOA7-negative patients was 100.965±2.485 months." (PMID 38699661, 2024). "The data from the breast cancer cell studies (knockdown of NCOA7 expression) indicated that diminishing NCOA7 expression in breast cancer cells inhibited cell proliferation and migration." (PMID 38699661, 2024). "The overall survival of the NCOA7-positive patients with breast cancer was significantly lower than that of the NCOA7-negative patients (χ2=7.423, P=0.006)." (PMID 38699661, 2024). "The expression of NCOA7 was knocked down in the breast cancer cell lines T47D and MCF7 by the lentiviral vector loaded with NCOA7 shRNAs along with the control shRNA-transfected cell line that expressed a luciferase shRNA (shLuc)." (PMID 38699661, 2024). "Currently, the molecular mechanism by which NCOA7 promotes breast cancer progression remains to be elucidated." (PMID 38699661, 2024). "The nuclear receptor co-activator protein NCOA7 is a potential prognostic biomarker of breast cancer, a possible driver protein for breast cancer progression and a potential target for anti-metastatic therapy for advanced breast cancer." (PMID 38699661, 2024).
breast carcinoma (continued). "The large majority (10/13) of these genes were reported to play a role in the regulation of estrogen and/or progesterone response in human breast cancer (NCOA7:; NCOA3:; USP22:; MED24:; CCAR1:; CRY2:; STAT5B:; PAGR1:; TAF1:; PHB2:)." (PMID 35996163, 2022). "As a matter of fact, NCOA7 was previously immunoprecipitated with AhR in human breast cancer cells using AhR-specific antibodies." (PMID 31481962, 2019). "However, the role of NCOA7, as an ER-binding protein, in regulating breast cancer progression has remained elusive." (PMID 38699661, 2024). "In addition, NCOA7 will be established as a poor prognostic biomarker and a target molecule for breast cancer therapy." (PMID 38699661, 2024). "However, limited experimental data have shown the role of NCOA7 in oxidation resistance or have examined the TLDc domain required for NCOA7 to promote breast cancer cell proliferation or migration." (PMID 38699661, 2024). "Therefore, NCOA7 may exert an anti-oxidative function and protect breast cancer cells from the damage of oxidative stress." (PMID 38699661, 2024). "It was initially expected that NCOA7 may promote breast cancer progression via ER signaling." (PMID 38699661, 2024). "Furthermore, NCOA7 may be considered to be a driver protein for breast tumor growth and metastasis and a potential therapeutic target for breast cancer, notably for advanced breast cancer." (PMID 38699661, 2024). "The overall survival of patients with NCOA7-positive breast cancer was significantly lower than that of patients with NCOA7-negative breast cancer (P=0.006)." (PMID 38699661, 2024). "Given these known molecular interactions of NCOA7, it is speculated that it promotes breast cancer progression through a complex regulatory network, not just its ER co-activator activity." (PMID 38699661, 2024). "Furthermore, knockdown of NCOA7 expression in breast cancer T47D and MCF7 cells significantly inhibited both cell proliferation and migration, suggesting that this protein may exert a role in driving breast cancer progression." (PMID 38699661, 2024). "However, the results of the present study indicate that the expression levels of NCOA7 are preferentially associated with the clinicopathological parameters of TNBC, suggesting that the oncogenic effect of NCOA7 on breast cancer, at least in TNBC, may not be mediated via ER signaling." (PMID 38699661, 2024).
oral squamous cell carcinoma (5 papers, 2016 to 2023). "The overexpression of NCOA7 promotes the proliferation of oral squamous cell carcinoma cells by activating the aryl hydrocarbon receptor (AHR)." (PMID 37511343, 2023). "Furthermore, the high expression of NCOA7 in oral squamous cell carcinoma has been suggested as a potential biomarker of the disease." (PMID 35256587, 2022). "In another study, NCOA7 was identified as a potential biomarker in oral squamous cell carcinoma." (PMID 31481962, 2019).
clear cell renal cell carcinoma (4 papers, 2023 to 2025). "Nuclear receptor coactivator 7 (NCOA7) is a conserved nuclear receptor coactivator with potential prognostic relevance in clear cell renal cell carcinoma (ccRCC)." (PMID 40282346, 2025). "Furthermore, NCOA7 expression levels were significantly decreased in all three subtypes of RCC (clear cell renal cell carcinoma, ccRCC; kidney chromophobe, KICH; kidney renal papillary cell carcinoma, KIRP) compared with healthy paracancerous tissues of RCC." (PMID 37511343, 2023). "However, the expression and prognostic significance of NCOA7 in clear cell renal cell carcinoma (ccRCC) remain unknown." (PMID 37511343, 2023). "However, the prognostic effects and molecular biological processes of NCOA7 in clear cell renal cell carcinoma remain unexplored, and it remains unclear whether it is involved in ccRCC progression." (PMID 37511343, 2023).
neuroblastoma (4 papers, 2016 to 2025). Neuroblastoma (NB) is the most common solid, extracranial childhood tumor. "Using a mouse neuroblastoma cell line, Neuro-2A, immunofluorescence analysis showed Ncoa7 in the perinuclear region, overlapping with GRASP55, but no detectable expression of Oxr1." (PMID 40445757, 2025). "NCOA7 is found to regulate all-trans retinoic acid-mediated neuronal differentiation, and it serves as a good prognostic indicator for neuroblastoma." (PMID 37511343, 2023). "In addition, levels of NCOA7 are reported to correlate with the clinical outcome of neuroblastomas." (PMID 26668325, 2016). "Recently, individual studies demonstrated that NCOA7 regulated all-trans-retinoic acid (ATRA)-mediated neuronal differentiation and functioned as a favourable prognostic indicator for neuroblastoma." (PMID 27509054, 2016).
viral infection (3 papers, 2019 to 2025). "NCOA7 inhibited wild-type virus infection by ~6-fold, whereas infection with ΔPRRA Spike bearing virus was inhibited by ~3-fold, an ~50% decrease in NCOA7 sensitivity." (PMID 34807954, 2021). "More recently, the same interferon-inducible isoform of NCOA7 was found to mediate immunoregulatory effects in antigen presenting cells in a model of viral infection." (PMID 31481962, 2019). "We used ectopic expression and gene knockout to demonstrate that NCOA7 inhibits SARS-CoV-2 Spike pseudotyped virus and replication-competent virus infections in lung epithelial cells." (PMID 34807954, 2021).
autism (2 papers, 2021 to 2022). Persistent deficits in social interaction and communication and interaction as well as a markedly restricted repertoire of activity and interest as well as repetitive patterns of behavior. "Up to date, there is only a single recessive case of autism known to be due to mutation in nuclear receptor coactivator 7 (NCOA7), and very little is known about NCOA7 function in neuronal physiology." (PMID 36466804, 2022). "Then, more recently, systematic analysis of exome data from the Autism Sequencing Consortium identified a recessive case of ASD caused by a homozygous nonsense mutation in NCOA7." (PMID 33340069, 2021). "Furthermore, with specific relevance to the recent discovery of NCOA7 mutations in autism, several de novo genetic variants in the nuclear receptor corepressors NCOR1 and NCOR2 are found in pediatric patients with intellectual disabilities or ASD." (PMID 33340069, 2021). "This overall reduction of the inhibitory circuitry observed in Ncoa7 mutant mice may affect the connectivity between cortical and ventral brain areas involved in the regulation of anxiety and sociability, behavioural outcomes relevant to the recent association of the gene to autism." (PMID 33340069, 2021). "Unlike conventional ASD risk genes, the correlation of nuclear receptor coactivator (NCOA7) with autism pathogenesis was revealed through the multidimensional examination of shared co-expression relationships of previously identified autism candidate genes with normal neurodevelopmental processes." (PMID 36466804, 2022). "For example, nuclear receptor coactivator 7 (NCOA7) has been associated with autism, although almost nothing is known regarding the mode-of-action of this TLDc protein in the nervous system." (PMID 33340069, 2021). "The viability of our new DEL model thus allowed us to investigate whether the absence of Ncoa7 would cause behavioural alterations relevant to the gene’s known links to autism, or other features observed in TLDc gene rodent models, such as ataxia." (PMID 33340069, 2021). "Therefore, in view of the recent association of NCOA7 loss-of-function mutations in autism, and the distinct lack of knowledge regarding NCOA7 function in the nervous system, we investigated neuronal V-ATPase function in vivo using our new Ncoa7 deletion model." (PMID 33340069, 2021).
lymph node metastasis (2 papers, 2016 to 2024). "Among the patients with lymph node metastasis, the overall survival was reversely associated with the expression of NCOA7 (P=0.042)." (PMID 38699661, 2024). "Additional statistical analysis indicated that the expression of NCOA7 was associated with patient age, tumor size and lymph node metastasis in patients with triple-negative breast cancer (TNBC) compared with that in patients with non-TNBC." (PMID 38699661, 2024). "As shown in Table SII, the expression of NCOA7 was significantly higher in patients with TNBC than in patients with N-TNBC who were aged >50 years (P=0.023), with a tumor size of >3 cm (P=0.007) and those who had lymph node metastasis stages N1-3 (P=0.023)." (PMID 38699661, 2024).
multiple sclerosis (2 papers, 2017 to 2019). A progressive autoimmune disorder affecting the central nervous system resulting in demyelination. "A more recent study has highlighted the importance of distinguishing these NCOA7 isoforms; in peripheral blood mononuclear cells from multiple sclerosis patients treated with IFNβ1b, a unique short NCOA7 isoform was significantly induced by more than 60-fold only 4 h post-IFNβ1b treatment." (PMID 28707022, 2017). "Interferon β1b, commonly used as therapeutic agent in multiple sclerosis (i.e., an inflammatory/autoimmune disease) induces the expression of an alternative-start transcript of the human NCOA7 gene, which may be involved in the protection from inflammatory oxidative stress." (PMID 31481962, 2019).
prostate carcinoma (2 papers, 2017 to 2024). A carcinoma that arises from epithelial cells of the prostate gland. "Moreover, the expression of NCOA7 can be regulated by nuclear receptor ligands themselves; for instance, 1.0 nM androgen significantly reduces the expression of NCOA7 by 40% in prostate cancer cells." (PMID 28707022, 2017).
schizophrenia (2 papers, 2017 to 2021). A major psychotic disorder characterized by abnormalities in the perception or expression of reality. "The network analysis of the 7 annotated genes revealed 5 networks, each with PARK2, N4BP2, KCNIP4, ADGRL2, or NCOA7 as its focus gene, which may have joint influence on the initiation of schizophrenia." (PMID 28744025, 2017).
Anxiety (1 paper, 2021). Intense feelings of nervousness, tension, or panic often arise in response to interpersonal stresses. "Our developmental expression data show that Ncoa7 is found in all of these key neuroanatomical regions, in addition to those related to olfaction, a fundamental feature of mouse exploratory activity, anxiety and sociability." (PMID 33340069, 2021).
Autoimmunity (1 paper, 2019). The occurrence of an immune reaction against the organism's own cells or tissues. "Therefore, although its functions have not been completely understood, NCOA7 may contribute to immunoregulatory mechanisms that can be either pathogenetic (i.e., in neoplasia) or protective (i.e., in autoimmunity), similarly to AhR." (PMID 31481962, 2019).
breast tumor (1 paper, 2024). "This confirmed the results obtained from the breast tumor IHC staining studies indicating that the expression levels of NCOA7 were associated with breast tumor growth and metastasis." (PMID 38699661, 2024). "This will explore the association of NCOA7-mediated ER regulation, anti-oxidation and/or vesicle trafficking signaling pathways with breast tumor growth and metastasis." (PMID 38699661, 2024). "Statistical analysis of the difference in expression of NCOA7 between the breast tumor and the adjacent normal tissue samples indicated that the expression of NCOA7 in breast tumor tissues was significantly higher than that in the adjacent normal tissues (P<0.001)." (PMID 38699661, 2024). "NCOA7 was positively expressed in 44% of breast tumor tissues." (PMID 38699661, 2024).
colon adenocarcinoma (1 paper, 2024). "NCOA7 expression is higher in the low-risk colon adenocarcinoma patients and shows a negative association with the risk score in an immune-associated risk model for colon adenocarcinoma prognosis." (PMID 38166604, 2024).
colorectal cancer (1 paper, 2025). A primary or metastatic malignant neoplasm that affects the colon or rectum. "Conversely, the suspected dysplasia was characterized by the expression of CXCL2/3 (inflammatory markers), LCN2 (a secretory protein potentially acting as a tumor suppressor in colorectal cancer), and SOD2 and NCOA7 (stress response genes)." (PMID 40667282, 2025).
distal renal tubular acidosis (1 paper, 2023). A kidney disorder of impaired net acid secretion by the distal tubule characterized by hyperchloremic metabolic acidosis. "A previous study confirmed that NCOA7 is highly expressed in the kidney and the involvement of NCOA7 mutations in the pathogenesis of distal renal tubular acidosis." (PMID 37511343, 2023).